TLR4 (toll like receptor 4)
Diseases named in the same sentence as TLR4 in open-access papers (continued):
Sharing a sentence is not in itself a finding about the gene and the disease.
infection (continued). "Moreover; significant association between TLR2 polymorphisms, TLR4 Arg753Gln polymorphisms and risk of infections in AML patients was documented." (PMID 33247673, 2020). "Recent studies have also shown that pyroptosis may be activated through sterile inflammation (non-infection) via activation of TLR4 by damage-associated molecular patterns (DAMPs)." (PMID 33316945, 2020). "However, mice deficient in specific molecules of the immune system, such as C3H/HeJ mice (tlr4−/−), are highly susceptible to lethal infection with L. interrogans serovar Icterohaemorrhagiae and Copenhageni." (PMID 30616505, 2019). "However, TLR4 receptor engagement by GIPL does not provide long term benefit on disease pathogenesis as wild type TLR4 mice still succumb to infection, although at a later time than TLR4 deficient mice." (PMID 31145733, 2019). "AS is a chronic disease that requires long-term treatment, merely inhibition of TLR4/NF-κB may cause other potential adverse effects (such as infection and cancer) or other complications." (PMID 31402870, 2019). "Moreover, infection with L. donovani in Neu1-transfected cells showed enhanced TLR4-MyD88 association." (PMID 31649671, 2019). "Therefore, mouse TLR4 is necessary to restrict S. Typhimurium proliferation and promote host survival during infection with the evolved pbgA-lpxC suppressor variants." (PMID 31611279, 2019). "In these females, systemic blockage of TLR4 signaling significantly reduced preterm delivery and fetal death, indicating that the triggering of TLR4 by microbial components is a pathogenesis factor in pregnancy disturbances caused by infection." (PMID 29440369, 2018). "For example, in vivo, in a C3H/HeJ murine infection model deficient in TLR4 signaling pathway, a higher mycobacterial burden was evident in the lungs, spleen, and liver, and the survival rate of the TLR4-deficient mice was lower following infection compared with WT mice." (PMID 29637049, 2018). "The let-7 family of miRNAs has been associated with regulation of toll-like receptor 4, control of cytokine levels, and regulation of the NFκB pathway in response to infection." (PMID 30619110, 2018). "Furthermore, the donor toll-like receptor 4 +3725G/G genotype was associated with a significantly lower incidence of fatal infections than other variations." (PMID 28484092, 2017). "However, TLR4-deficient mice immunized with DnaJ-ΔA146Ply were provided a certain amount of protection against pneumococcus lethal infection." (PMID 28659923, 2017). "However, blocking TLR4 in humans, as a therapeutic approach must be considered cautiously, because attenuated TLR4 function, seen in human TLR4 SNP variants, increases the susceptibility to infection." (PMID 28410596, 2017). "We therefore sought to determine the putative protective role that TLR4 antagonists may have on infections caused by the filoviruses EBOV and the closely related Marburg virus (MARV) in murine models." (PMID 28442605, 2017). "The lower translational activity associated with the TLR4 +3725G/G genotype may contribute to prevent infection-associated death following SCT." (PMID 28484092, 2017). "Genotyping of Asp299Gly and Thr399Ile SNPs in CL caused by L. major showed a higher frequency (40.9%) in patients with chronic disease compared to individuals with asymptomatic infection (13.3%) suggesting the involvement of TLR4 in susceptibility and severity of CL." (PMID 28241747, 2017). "In contrast to humans, the ability of mice to recognize Leptospira LPS and Lipid A through TLR4 and MyD88 independent mechanisms, may explain some of the observed differences between humans and mice regarding susceptibility to infection." (PMID 27486445, 2016). "Our data demonstrate that specific inhibition of TLR4-activated JNK signalling pathways has potential as a therapeutic approach in the management of infection/inflammation-associated PTL and prevention of the associated detrimental effects to the neonatal brain." (PMID 26183892, 2015).
infection (continued). "Polymorphisms in the TLR4 gene have been associated with different infectious diseases in humans, such as meningitis and tuberculosis, as well as some types of cancers and with infection and disease in cattle, chicken and pigs." (PMID 24566961, 2014). "We also studied the expression of TLR4 and found that the behavior of the four tested strains (26695, virB4–, virD4–, and 8822) was similar, causing no significant reduction in TLR4 expression, even 24 h after infection." (PMID 23755130, 2014). "Schröder and Schumann (Schröder and Schumann 2005) suggested that mutations in the TLR4 regions involved with pathogen recognition and transduction signaling may affect host susceptibility to infection." (PMID 24566961, 2014). "Common genetic variants of genes functionally linked to inflammation and immunity such as COX-2, RNASEL and TLR4 have been associated with prostate cancer risk suggesting that infection and host response to infection may be involved in its development." (PMID 25106851, 2014). "Here, we report that luminal release of exosomal vesicles is an important component of Toll-like receptor 4 (TLR4)-associated gastrointestinal epithelial defense against infection by Cryptosporidium parvum, an obligate intracellular protozoan that infects gastrointestinal epithelial cells." (PMID 23592986, 2013). "The authors observed diminished parasite load at the skin lesions of infected mice at the initial stages of infection, that is, 24 h, and found increased parasite survival in host cells from TLR4-deficient mice, which correlated with a higher activity of arginase." (PMID 22523644, 2012). "The role of TLR4 in infection was examined in TLR4-deficient mice." (PMID 21738466, 2011). "TLR4-deficient C3H/HeJ mice have an increased microbial burden and mortality after infection." (PMID 20964825, 2010). "Also, 4 h after infection, the percentage of TLR4-deficient macrophages infected with T. cruzi is significantly higher when compared to WT cells." (PMID 20442858, 2010). "The presence of TLR4 mutations in combination with TIRAP/Mal variants - either homozygous or heterozygous - resulted in a statistically significant increase in the risk of severe infections." (PMID 20525286, 2010). "Therefore, the effects of TLR4 deficiency on susceptibility to infection with T. cruzi are more evident in the C3H background." (PMID 20442858, 2010). "cruzi microbicidal activity of WT and TLR4-deficient macrophages, it was first necessary to investigate whether the infection rate and parasite load were equivalent in both cases." (PMID 20442858, 2010). "The survival rate of young chicks derived from a backcross between lines W1 and C and infected intra-muscularly one day post-hatch with S. Typhimurium was linked to SLC11A1 and TLR4, which, together, explained up to 33% of the differential resistance to infection." (PMID 20429884, 2010). "Importantly, NleE was found to be required for full virulence of C. rodentium upon infection of wild-type mice, but this requirement was diminished upon infection of mice deficient in TLR4." (PMID 20126447, 2010). "We then analyzed whether a lower NO production by the infected TLR4-deficient mice could explain their higher susceptibility to infection as suggested by the results obtained in vitro." (PMID 20442858, 2010). "To examine whether FimH plays a role in innate immune induction in the context of a natural infection, we measured PMN leukocyte recruitment to the urinary tract in B6 mice and TLR4-deficient mice following infection with wild type UPEC and a fimH null mutant." (PMID 19057665, 2008). "This underlines the crucial role of TLR4 pathway in the innate recognition of pathogens but may also reveal microbial strategies evolved to facilitate infection." (PMID 17389921, 2007). "Finally, the researchers tested the ability of TLR2- and TLR4-deficient mice to survive after infection with live B. pseudomallei." (PMID 17676990, 2007).
infection (continued). "Presence of Th1 dependent IgG2a in C3H-HeN mice at two weeks post infection with L. interrogans suggests that this response may be driven in part by TLR4 which has been associated with resistance and may explain why disease progression in this mouse is less pronounced than C3H-HeJ." (PMID 39975062, 2025). "Despite expecting TLR4-deficiency and pre-treatment with a TLR4 agonist to have opposing effects, our data imply that any perturbation of TLR4 signalling affects scavenger receptor expression which could impact macrophage response to infection." (PMID 37580395, 2023). "TLR4 induction has been found in epithelial cells (including lung cells) that are in contact with the external environment, and pathogenic infections could potentially affect lung cell physiology through TLR4-mediated local infection or inflammatory responses." (PMID 33559732, 2021). "A possible factor underlying susceptibility to infection in humans may be a lack of recognition of leptospiral-LPS by human TLR4, whereas resistance in mice has been linked to production of antibody within 48-72h post infection and the murine TLR4 ability to engage leptospiral-LPS." (PMID 34249775, 2021). "Hence, C. coli could stably establish within the gastrointestinal tract of hma TLR4-deficient IL10-/- mice until 21 days post-infection." (PMID 32443576, 2020). "Therefore, molecular patterns associated with infection and/or brain cell damage may activate TLR4 and Ca2+ signaling, an effect exacerbated during neuronal aging." (PMID 32983082, 2020). "Thus, we propose an inverse correlation of decreased Neu1 on the surface of these parasite-infected macrophages and enhanced sialic acids on TLR4 with reduced Neu1-TLR4 association and reduced activation, which is a prerequisite event for establishing a successful infection." (PMID 31649671, 2019). "Therefore, the high sensitivity demonstrated by the Myd88−/− Trif−/− double deficient mice to infection is in accordance with a role for TLR4 and/or TLR3 in the response against T. cruzi, as these members of the TLR family are the only known to use TRIF as a transducer molecule." (PMID 22496959, 2012). "It has been demonstrated that the low-functioning TLR4 polymorphisms may result in a reduced inflammatory response associated with a low-damaging infection resulting in persistent infection, whereas TLR4 mRNA was up-regulated in gastric epithelial cell lines infected with H. pylori." (PMID 23554619, 2010). "In accordance with that hypothesis, the production of NO (inferred from nitrite levels in the supernatants) by spleen cells from infected TLR4-deficient mice was significantly reduced when compared with NO released by spleen cells from infected WT mice at day 10 post-infection." (PMID 20442858, 2010). "Glucocorticoids modulate TLR expression; hence, we investigated whether the elevated iNOS expression observed on day 4 of infection in dexamethasone-treated mice was due to enhanced TLR4 expression causing an increased sensitivity of the mice to S. Typhimurium lipopolysaccharide." (PMID 19049646, 2008). "The TLR4 signaling pathway results in activation of NF-κB and interferon regulatory factor 3, suggesting that TLR4-deficient mice would have increased viral replication because of impaired cytokine production and recruitment of immune cells to the lung and other sites of infection." (PMID 18802464, 2008). "Interestingly, even though its activation is delayed, among the three MyD88 is the most important molecule for host defense against Brucella infection in vivo, since MyD88 knockout (KO) mice are more susceptible to infection when compared to TLR4, TLR2, TLR4/TLR2 KO mice." (PMID 16556309, 2006). "The infection with S. Typhimurium LT2 significantly increased TLR4 mRNA in the ileum compared to the other groups." (PMID 41474380, 2026). "The infection with S. Typhimurium significantly increased TLR4, MD‐2, LBP, CD14, and MyD88 mRNA in both parts of the intestine." (PMID 41474380, 2026).
infection (continued). "Extracts were prepared by aqueous solid-liquid extraction and tested in lipopolysaccharide (LPS)-stimulated RAW264.7 and THP-1 macrophages, HEK-Blue TLR4 reporter cells, and Drosophila melanogaster models of intestinal inflammation and infection." (PMID 42188317, 2026). "The previous colonization with DPM significantly limited TLR4 mRNA expression after subsequent infection with LT2 (DPM + LT2) in the piglets infected with LT2 without the previous DPM treatment (LT2)." (PMID 41474380, 2026). "The results revealed the activation of the TLR4/MD‐2 complex and downstream signaling by the infection." (PMID 41474380, 2026). "To better understand the distribution of TLR4 in cecum tissues, which is the most affected intestinal segment during mouse infection, at the peak of clinical symptoms, we performed immunohistochemistry." (PMID 41261342, 2025). "Here, we extend these findings by showing that infection with ST resulted in prolonged PT and elevated TAT complexes in TLR4-deficient mice, though to a lesser level compared to those observed in C57BL/6 mice." (PMID 41304196, 2025). "The results showed that high level-/long time-H37Ra infection downregulated the phosphorylation level of NF-κB as well as the expression of TLR4, TRAF6, and MyD88." (PMID 40502714, 2025). "At 0 h post-infection (hpi), PRV infection caused a significant increase in the protein expression of TLR4, MyD88, and NF-κB p65 compared with the blank control group (p < 0.05)." (PMID 40308697, 2025). "Male C57BL/6 mice were infected with C. difficile, and cecum samples were analysed 3 days post‐infection for TLR4 expression." (PMID 41261342, 2025). "tlr4 mutant mice infected with 108 CFU also cleared infection relatively early after inoculation, with most mice having no detectable bacteria in the lungs by ~7 dpi." (PMID 40817088, 2025). "For example, at 11 DoA (4 days post infection), TLR4 and CSF2RA expressions were correlated to Enterococcus and IL18 (a pro-inflammatory cytokine known for its ability to enhance the production of interferon-gamma) to Salmonella." (PMID 40079593, 2025). "In the context of APP infection, it has been reported that APP virulence factors stimulate TLR4 signalling in the early stages of infection, leading to an inflammatory response." (PMID 39831520, 2025). "Given the unexpected result that tlr4 mutant mice exhibit chronic infection at lower inoculums, while WT and tlr4 mutant mice clear infection at higher inoculums, we sought to characterize the host immune response in these different conditions." (PMID 40817088, 2025). "Here, we demonstrate that low intranasal inoculums in tlr4 mutant mice allows for infections lasting at least 3 weeks." (PMID 40817088, 2025). "A previous study demonstrated that the activation of TLR4 leads to the phosphorylation of NF-κB, a key regulator of inflammation and infection outcomes." (PMID 40872941, 2025). "Strikingly, while WT mice infected with a lower dose of 105 bacteria cleared infection after 1 day, tlr4 mutant mice maintained detectable bacteria in the lungs out to the latest timepoint tested in this experiment, 19 dpi." (PMID 40817088, 2025). "At the higher inoculum of 108 CFU, G654 infection was inconsistent in tlr4 mutant mice and infection was cleared early after infection in WT mice." (PMID 40817088, 2025). "Dynamic network comparative analysis identifies critical time points for regulatory shifts, such as the transition point from TLR4-MyD88 dominance to TLR4-TRIF dominance (which occurs on average at 32 ± 5 hours post-infection)." (PMID 40861459, 2025). "Regarding kidney markers of inflammation and fibrosis, C3H-HeN and C57BL/6 produced less IL-1 beta, iNOS and ColA1 than C3H-HeJ, which is consistent with increased resilience to infection expected of the tlr4 competent strains." (PMID 39975062, 2025).
infection (continued). "C57BL/6 male mice deplete in TLR4, or C3G/HeJ male mice with a missense point mutation that lacks TRL4 only in the cytoplasm, both show reduced sensitivity to LPS, suggesting that TLR4 is required for infection responses." (PMID 39968295, 2025). "PRV infection upregulated TLR4, MyD88, and NF-κB p65 protein expression during the pre-infection phase, followed by their downregulation after 12 h." (PMID 40308697, 2025). "At the lower inoculum, although WT mice clear infection within nearly 24 h and tlr4 mutant mice maintain infection out to at least 3 weeks, minimal significant differences in inflammatory cytokines were observed." (PMID 40817088, 2025). "An in vitro infection of murine BMDMs isolated from TLR2-, TLR3- TLR4-, TLR7-, TLR9-, TLR2/TLR4-, and TLR2/TLR4/TLR9- deficient mice and cultured with Mtb showed that TLR9 was critical for protection against infection via FLT-3 ligand-generated DCs." (PMID 41236793, 2025). "Our data shows that susceptibility to sublethal infection can be observed in 9–10 week old C3H/HeN and C57BL/6 mice, which express competent TLR4." (PMID 40445994, 2025). "There are numerous links between competent recognition of Leptospiral LPS by TLR4 and resistance to infection in mice." (PMID 39975062, 2025). "Key upstream receptors (TLR4, C5aR1) and downstream cytokines were analyzed to determine how infection activates TLR4–NF-κB- and GPCR-mediated pathways, and to evaluate the modulatory effects of L-Sepiapterin and CDDO-Me." (PMID 41294830, 2025). "HMPV-N mRNA and protein levels were also elevated in TLR4-overexpressing cells at 20 h post-infection." (PMID 41346628, 2025). "Among FcγRs, FcγRI emerged as the dominant ADE mediator: its blockade most effectively attenuated infection, while dual FcγRI/TLR4 inhibition abolished ADE." (PMID 40557164, 2025). "In contrast, HMPV-induced TNF mRNA expression in MDMs was significantly reduced at 3 h post-infection following silencing of either SLAMF1 or TLR4." (PMID 41346628, 2025). "Myd88-deficiency attenuated secretion of IL-6 and TNFα upon infection with CFT073, while tlr4-deficiency almost completely abolished secretion of both cytokines." (PMID 41310197, 2025). "Infection of Tlr4-/- and Casp11-/- mice showed that extracellular LPS sensing via TLR4 is required in our model." (PMID 40113753, 2025). "Despite this long infection course in tlr4 mutant mice at this dose, dissemination to distal organs was rarely detected." (PMID 40817088, 2025). "Upon activation, TLR4 triggers innate immune responses in macrophages and dendritic cells, contributing to the control of the enterotoxigenic infection spread." (PMID 39953722, 2025). "Inflammation begins when innate immune cells detect infection or tissue damage through pattern recognition receptors (PRRs), such as Toll-like receptor-4 (TLR4)." (PMID 41462950, 2025). "In terms of anti-infection, clinical trials of TLR4 agonists for certain refractory infections are underway to confirm their efficacy and safety for clinical treatment." (PMID 41568029, 2025). "TLR4 can regulate infection induction or the inflammatory response through endogenous molecules and apoptotic processes." (PMID 40378103, 2025). "In platelets, PLAUR was positively associated with TLR2, TLR4, TLR8, and RIG-I, and with infection these associations changed to TLR7 and LGP2 but continued to correlate with TLR4 and TLR8." (PMID 40825056, 2025). "Toll-like receptor 4 (TLR4) is a pattern recognition receptor that plays an important role in the body’s response to infection and injury by mediating pro-inflammatory responses through activation of the NF-κB signaling pathway." (PMID 41488621, 2025). "In this study, we uncovered a previously unrecognized role of TLR4 in regulating brain endothelial responses during ExPEC infection." (PMID 40821830, 2025).